CXCR4 (C-X-C motif chemokine receptor 4)
Diseases named in the same sentence as CXCR4 in open-access papers (continued):
Sharing a sentence is not in itself a finding about the gene and the disease.
melanoma (continued). "Furthermore, circulating melanoma cells have been described to interact with perivascular MSCs through CXCR4/CXCL12 signaling and melanoma cell adhesion molecule (MCAM, CD146) in vivo, an interaction shown to be required for BM invasion." (PMID 33287630, 2021). "Melanoma patients with higher CXCR4 expression show poorer overall survival." (PMID 34806028, 2021). "More specifically for melanoma, it has been found in murine models that organ-specific extracellular proteins in the lungs and chemokine receptors, such as CXCR4, in the primary melanoma may mediate the preferential metastases in the lungs." (PMID 34503242, 2021). "The expression of CXCR4 by melanoma cells in patient samples has been correlated with the likelihood of pulmonary metastasis and increased pulmonary metastasis has been seen in mice inoculated with melanoma cells overexpressing CXCR4, with CXCR4 inhibition reversing this effect." (PMID 34830780, 2021). "Expression of CXCR4 correlates well with recurrence, metastasis, and survival in melanoma and CRC." (PMID 34298991, 2021). "X4-136, another CXCR4 inhibitor, could serve as a monotherapy or combined with immune checkpoint inhibitors in the treatment of melanoma and renal cell carcinoma." (PMID 34568309, 2021). "In addition to CLL, CXCR4 is overexpressed in over 23 cancers, including lung, prostate, melanoma, and uterine cancers." (PMID 34368645, 2021). "In addition, FTO level was found to be increased in human melanoma, knockdown of which increases m6A methylation in PD-1, CXCR4, and SOX10, leading to increased RNA decay through the m6A reader YTHDF2." (PMID 33611339, 2021). "This apparent difference from our data may probably imply specific molecular mechanisms which critically drive the osteotropism of melanoma cells like those affecting the SDF1/CXCR7/CXCR4 pathway, as recently proven." (PMID 33042809, 2020). "Similarly, 5-aza treatment increased CXCR4 mRNA and protein levels in melanoma cells, and concomitantly enhanced cell migration." (PMID 32110952, 2020). "We also selected CXCR4 (C-X-C motif chemokine receptor 4), since this gene was shown to be a direct target of miR-126-3p in colon and thyroid cancer cells and the CXCR4/CXCL12 (C-X-C motif chemokine ligand 12) axis is known to promote melanoma cell proliferation and invasiveness." (PMID 31227006, 2019). "Moreover, genetic deletion of CXCR4 in myeloid cells (CXCR4MyeΔ/Δ) significantly reduced melanoma tumor growth enhancing the NK antitumor immune response." (PMID 31661001, 2019). "Aim of the work was to evaluate Pep R in potentiating the anti–PD-1 efficacy in two syngeneic murine models, the colon cancer MC38 cells and the B16 melanoma model –human CXCR4 transduced, respectively reported to be immune responsive and immune resistant cancer models." (PMID 31661001, 2019). "Moreover, the effect of targeting tumoral intrinsic PD-1, as T cell-independent effect, plus CXCR4 antagonism was evaluated in PES43 human melanoma CXCR4 expressing xenografts." (PMID 31661001, 2019). "In addition, the CXCR4 antagonist Peptide R54 potentiates the inhibition of cell-intrinsic PD-1, T cell-independent response, in human melanoma xenograft providing relevant information for combinatorial approaches to enhance antitumor immunity." (PMID 31661001, 2019). "The B16 mouse melanoma cell line constitutively expresses CXCR4." (PMID 30420855, 2018). "Altogether, CXCR4 is involved in the metastatic spreading of melanoma cells and therefore may influence patient outcomes." (PMID 30420855, 2018). "This supports the notion that increased CXCR4 expression on lymphocytes of melanoma patients could be further studied as a potential predictive and/or follow-up biomarker." (PMID 29682201, 2018). "Notably, genetic deletion of CXCR4 in myeloid cells in a melanoma mouse model fostered NK cell-mediated antitumor immunity suggesting indirect suppression of NK cell activity by CXCR4 signaling." (PMID 30622535, 2018).
melanoma (continued). "Notably, migration of cytotoxic T lymphocytes (CTLs), derived from two melanoma patients, to autologous tumor cells depended on their expression of CXCR4." (PMID 29682201, 2018). "Intra-arterially injected circulating CXCR4-expressing melanoma cells require SDF-1 signaling by mesenchymal stem cells that act as pericytes for extravasation to bone and liver and perivascular niche formation as demonstrated by humanized heterotopic bone formation assay." (PMID 30622535, 2018). "Additionally, VGVAPG enhances CXCR4/SDF1α mRNA and protein expression in melanoma cell lines, further highlighting the chemotactic and potential immunomodulatory nature of such peptides." (PMID 27369317, 2016). "CXCR4 signaling may regulate metastasis of chemoresistant melanoma cells by a lymphatic premetastatic niche." (PMID 28036019, 2016). "Interestingly, melanoma growth in mice receiving Bay60-6583 was attenuated by inhibition of the CXCL12/CXCR4 pathway with AMD3100." (PMID 27590504, 2016). "Indeed, circulating antigen-specific CD8+ lymphocytes constitutively express CXCR4 and the chemokine ligand can recruit cytotoxic T cells to melanoma cells in organotypic culture." (PMID 24961933, 2014). "Moreover, the receptors CXCR3, CXCR4, CCR7 and CCR10 have been implicated in the process of metastasis in melanoma, based on studies with animals." (PMID 24559071, 2014). "Notably, AMD11070, a novel orally bioavailable inhibitor of CXCR4, has been shown to abrogate melanoma cell migration independently from B-RAF wild-type and mutated status." (PMID 24971349, 2014). "We therefore investigated SDF-1, the ligand for the GPCR CXCR4, which has been associated with poor prognosis and malignancy of melanoma; but again, it was not measurably attractive to cells in our assays (compare with strong response to serum)." (PMID 25313567, 2014). "Interestingly, expression of CCR7 in B16 melanoma cells induces metastasis to the lymph nodes, while, as previously discussed, expression of CXCR4 in murine B16 cells increases metastasis to the lungs." (PMID 24259307, 2013). "Studies show that malignant melanoma expresses high levels of CCR10 in addition to CXCR4 and CCR7." (PMID 24259307, 2013). "Currently, CXCR4 is one of the most studied chemokine receptors and is over-expressed in over 20 different human tumors, including prostate, breast, ovarian, lung, pancreatic, colorectal, and melanoma." (PMID 23847541, 2013). "High levels of CXCR4 have been shown to correlate with the presence of metastatic disease in a wide variety of malignancies, including breast, prostate, lung, colorectal cancer, melanoma, and neuroblastoma." (PMID 21234386, 2011). "Analysis of CXCR4 expression in melanoma-infiltrated LNs indicated that high CXCR4 expression in LN metastases was correlated with shorter DFS and could be used as a prognostic marker in order to stratify melanoma patients at higher risk of progression." (PMID 24212647, 2011). "CXCR4 is expressed by various types of tumor cells, including breast, colorectal, gastric, ovarian, pancreatic, prostate, lung, melanoma, and brain tumor cells." (PMID 21880153, 2011). "Interactions between CXCL12 and CCL21, chemokines produced by lymph nodes and the CXCR7 and CXCR4 chemokine receptors expressed on melanoma cells, may have similar roles in mediating lymph node metastasis." (PMID 24212610, 2010). "AT-MSC showed tendency to decrease tumor incidence upon admixing to low 8MGBA glioblastoma cells dose, even though expression analysis has shown similar expression pattern for the 8MGBA except for constitutive CXCR4 expression in comparison to melanoma cells A375." (PMID 20509882, 2010). "It was reported that an excessive expression of CXCR4 on B16 melanoma cells enhances the metastatic accumulation of the cells in mouse lung, and that a CXCR4 antagonist T22 blocks pulmonary metastasis in mice injected with CXCR4-transduced B16 cells." (PMID 19787093, 2008).
melanoma (continued). "Thus, RUNX2 and CXCR4 represent two crucial molecules involved in melanoma progression." (PMID 38474372, 2024). "Hence, inhibition of the CXCR4/CXCL12 pathway may represent a viable therapeutic pathway in melanoma." (PMID 36923305, 2022). "Furthermore, CXCR4 signaling is utilized in melanoma cell metastasis through lymphatic vessels." (PMID 36158182, 2022). "Thus, CCR10 and CXCL12/CXCR4 may regulate homing of CD4+ Tregs to B16 melanoma tumors while invasion of NBL tumors by CD4+ Tregs is likely governed by CCL28/CCR10 and CXCL12." (PMID 34721405, 2021). "Studies show that CXCR4 plays an important role in metastasis of many cancers including breast, lung, colorectal, gastric, ovarian, prostate, pancreatic, melanoma, esophageal, head and neck, bladder, osteosarcoma, neuroblastoma, glioblastoma, and acute lymphoblastic leukemia." (PMID 24259307, 2013). "Additionally, it was shown that murine B16 melanoma cells express functional CXCR4 (respectively)." (PMID 22399057, 2012). "The SDF-1α/CXCR4 axis belongs to this class of mediators and recent studies have shown that inhibition of CXCR4 with antibodies, peptide antagonists or siRNA all reduce metastasis in several solid tumors, including breast, melanoma, pancreas, prostate and colon cancers." (PMID 19325708, 2009). "As for erasers, FTO can promote anti-PD-1 resistance by modulating m6 A methylation in several vital protumorigenic melanoma cell-intrinsic genes, PD-1, SOX10, and CXCR4." (PMID 40483535, 2025). "In acute myeloid leukemia, FTO was shown to control stem cell differentiation through the ASB2/RARA axis, and FTO was revealed to affect immunotherapy by regulating intracellular factors (PD-1, CXCR4, and SOX10) in melanoma." (PMID 38384328, 2024). "In conclusion, ANH from MLiM showed an upregulation in CXCR4 and COL1A1/2, while melanoma cells of MLiM showed a significant upregulation in TNF." (PMID 39496484, 2024). "In NGDSP analysis adjacent normal hepatocytes (ANH) had higher CXCR4 and COL1A1/2 levels than distant normal hepatocytes (DNH), while melanoma cells had higher TNF‐α levels." (PMID 39496484, 2024). "The experiments demonstrated the specificity of MLiM cell supernatant to induce CXCR4 and COL1A1/2 compared with metastatic cell lines of different cancer types as well as different melanoma organ metastasis." (PMID 39496484, 2024). "In this study, we identified that CXCR4 expression is dependent on RUNX2 in melanoma cells, shedding light on its role in melanoma invasiveness and osteotropism." (PMID 38474372, 2024). "Further research is warranted to fully elucidate the complex interplay between CXCR4, RUNX2, and autophagy in melanoma and develop targeted therapies to improve patient outcomes." (PMID 38474372, 2024). "In melanoma, knockdown of FTO promotes YTHDF2-mediated PD-1, CXCR4, and SOX10 mRNA decay, sensitizing melanoma cells to interferon-gamma and anti-PD-1 therapy." (PMID 36859310, 2023). "Meanwhile, CDKN2A, CXCR4 and RAD51 were significantly up-regulated in melanoma compared with normal skin except CDKN1A (significantly down-regulated)." (PMID 38070141, 2023). "Mavorixafor is an oral, selective, allosteric CXCR4 inhibitor being developed for the treatment of Warts, Hypogammaglobulinemia, Infections, and Myelokathexis (WHIM) syndrome, melanoma, and other liquid and solid tumors." (PMID 36923305, 2022). "In melanoma, FTO promoted cell proliferation and overall tumorigenicity by demethylating m6A on melanoma-promoting genes Pdcd1, Cxcr4, and Sox10." (PMID 35350378, 2022). "In melanoma, FTO promoted resistance to IFN γ-mediated cell death through m6A demethylation of pro-tumorigenic genes Pdcd-1, Cxcr4, and Sox10." (PMID 35350378, 2022). "This is in line with the results of a previous study showing overexpression of CXCL12 in B16 melanoma–repelling antigen-specific T cells, suggesting complex and fine-tuned control of Teff infiltration by CXCL12/CXCR4 signaling." (PMID 35552271, 2022).
melanoma (continued). "Demethylation of Pdcd-1, Cxcr4, and Sox10 prevented downstream YTHDF2-mediated mRNA decay, resulting in increased expression of these melanoma-promoting genes." (PMID 35350378, 2022). "For example, in melanoma, FTO expression reduces the methylation of SOX10, CXCR4, and PD-1 by m6A in key tumor-promoting melanoma cell-intrinsic genes to promote tumorigenesis." (PMID 36360287, 2022). "Blockade of CXCR4 by AMD3100 coupled with the cytotoxic drug dacarbazine significantly inhibited tumor growth and metastasis of melanoma compared to dacarbazine alone." (PMID 35145271, 2022). "In melanoma, CXCR4 is frequently expressed at increased levels, particularly in the CD133+ melanoma cell population believed to represent melanoma stem cells." (PMID 36923305, 2022). "It has been shown that YTHDF2 targets a plethora of mRNAs for degradation in cancers, such as, TNFR2, c-Myc and CEBPA in leukemia, EGFR, IL11, SERPINE2 and SOCS2 in liver cancer, and PD-1, CXCR4, and SOX10 in melanoma." (PMID 33658012, 2021). "In melanoma, we have recently shown that FTO promotes the mRNA stability of the melanoma-promoting genes PDCD1, CXCR4, and SOX1013." (PMID 33846348, 2021). "The current study aimed to investigate Salmonella suppresses CXCR4 protein expression and tumor cell migration ability in B16F10 melanoma and LL2 lung carcinoma cells." (PMID 34220311, 2021). "Treatment with blocking antibodies targeting CXCR4, the receptor for SDF-1, VEGF-A or IL-6, has been shown to reduce melanoma cell invasiveness induced by the conditioned media from hypoxic activated fibroblasts." (PMID 34067929, 2021). "In melanoma, FTO promoted the expression of PDCD1, which expresses the PD-1 protein, as well as CXCR4 and SOX10, promoting melanoma tumorigenesis and resistance to immunotherapy." (PMID 33669361, 2021). "For example, malignant melanomas express higher levels of CXCL1, CXCL2, and CXCL8 and receptors CXCR1, CXCR4, CCR10, and CCR7 compared with benign naevi." (PMID 34830780, 2021). "Agents targeting FAP-α, CXCR4/CXCL12, TGF-β, and other signaling in tumor stroma have been under preclinical study or clinical trials for various cancers including melanoma." (PMID 32373541, 2020). "Depleting FTO promotes the degradation of downstream genes PD-1, CXCR4, and SOX10 in an m6A-dependent manner, thereby sensitizing patients with melanoma to anti-PD-1 checkpoint blockade therapy." (PMID 33292526, 2020). "To validate these results, we further investigated the effects of BCM or h-Exos stimulation on protein levels of both CXCR4 and CXCR7 in melanoma cells." (PMID 31324252, 2019). "Consistently we found that IFNγ downregulates FTO in melanoma cells, and FTO mediates resistance to melanoma cell killing by IFNγ through its m6A demethylase activity and downstream targets PD-1 (PDCD-1), CXCR4, and SOX10." (PMID 31239444, 2019). "In our in vitro model, melanoma cells are endowed with different bone tropism, mostly depending on SDF-1/CXCR4/CXCR7 axis activation in response to bone microenvironment stimulation." (PMID 31324252, 2019). "In summary, we have demonstrated that FTO inhibition suppresses melanoma tumorigenicity and the expression of melanoma cell-intrinsic genes PD-1 (PDCD1), CXCR4, and SOX10, at least partially through YTHDF2-mediated mRNA decay." (PMID 31239444, 2019). "Melanoma cell lysates were analyzed by immunoblotting using antibodies against MMP7 and CXCR4, or against β-tubulin as a loading control." (PMID 31227006, 2019). "Knockdown of FTO increases m6A methylation in the critical protumorigenic melanoma cell-intrinsic genes including PD-1 (PDCD1), CXCR4, and SOX10, leading to increased RNA decay through the m6A reader YTHDF2." (PMID 31239444, 2019). "FTO knockdown increases m6A enrichment in the critical melanoma-promoting genes including PD-1 (PDCD1), CXCR4, and SOX10, and decreases their mRNA stability." (PMID 31239444, 2019).
melanoma (continued). "Herein, combined treatment of nivolumab + Pep R54 impaired tumor growth of human melanoma PES43 cells expressing PD-1 and CXCR4." (PMID 31661001, 2019). "According to this study the potential candidates for the melanoma tumor specific promoters were Cox-2, CXCR4, EGP-2, and survivin [done by comparison analysis in melanoma cell lines, primary melanoma cells, and HEMs (a normal melanocyte control)]." (PMID 31696058, 2019). "In melanoma, FTO impairs IFNγ-induced killing in melanoma cells in vitro via up-regulating PD-1, CXCR4, and SOX10 through suppressing YTHDF2-mediated-degradation and inhibits response to anti-PD-1 blockade immunotherapy." (PMID 31801551, 2019). "Herein the new CXCR4 antagonist Pep R strengthen anti-PD-1 efficacy in two murine cancer models, MC38 colon cancer and B16-hCXCR4 melanoma, respectively reported to be immune responsive and immune resistant cancer models." (PMID 31661001, 2019). "Thirdly, the use of specific CXCR4 inhibitors, T22 or a dimeric form of CXCL12, reduced lung metastases formation and inhibited the growth of primary melanoma tumors." (PMID 30420855, 2018). "AMD3100, a specific CXCR4 inhibitor, significantly suppressed tumor growth promoted by A2BR stimulation in melanoma-bearing mice." (PMID 27590504, 2016). "In a screen of several melanoma cell lines it was detected that the expression of chemokine receptors CCR7, CCR10, CXCR1, CXCR2 and CXCR4 can dramatically increase the rate of metastases and define their preferential site." (PMID 26197340, 2015). "We have also shown that the in vitro invasivity of ECFCs and in vivo ECFCs tumor homing depend on the interaction between CXCR4 of ECFCs and SDF1 released by MSCs and melanoma cells." (PMID 25003596, 2014). "We have evaluated, using flow cytometry, the expression of the chemokine receptors CXCR4, CXCR3, CXCR7, CCR7 and CCR10, at cell surface and intracellular levels, for thirteen human melanoma cell lines." (PMID 24559071, 2014). "In this study, murine melanoma B16 cells were injected into the tail vein of C57BL/6 CXCR4(+/+) and CXCR4(+/−) mice, reporting a significant reduction of lung metastasis in CXCR4(+/−) mice." (PMID 24971349, 2014). "Recently, immunohistochemical expression of CXCR4, CCR7 and CCR10 and their ligands has been described in tumor cells from primary and metastatic melanomas." (PMID 24559071, 2014). "For example, the coordinated interaction of CXCR4 and MT1-MMP is required for melanoma cell metastasis to lungs." (PMID 22496978, 2012). "Blood samples from patients with metastatic carcinoma (MC) or melanoma (MM) were enriched for CTC and expression of CR (CXCR4, CCR6, CCR7 and CCR9) was evaluated by flow cytometry." (PMID 22433180, 2012). "In addition, CXCR4 activates the AKT and NFκB signalling pathway in melanoma cells to promote cell survival and proliferation." (PMID 39496484, 2024). "In this system, the quantification of melanoma cell adherence to osteoblasts confirms their decreased infiltration level in the absence of RUNX2 or under CXCR4 inhibition." (PMID 38474372, 2024). "To verify the role of RUNX2 in promoting autophagy through CXCR4, we used RUNX2 KO melanoma cells." (PMID 38474372, 2024). "It is important to note that the CXCL12/CXCR4 axis activates the AKT and ERK cell signalling pathways, and we have recently demonstrated that a reciprocal activation between the RUNX2 and AKT/ERK pathways occurs in melanoma." (PMID 38474372, 2024). "We observed that melanoma cells express both RUNX2 and CXCR4." (PMID 38474372, 2024). "The limitation is that these previous studies focused on the CXCL12/CXCR4 function on metastatic melanoma cells but not in the adjacent cells that are part of the TME." (PMID 39496484, 2024). "All melanoma cells studied here expressed both RUNX2 and CXCR4 at the mRNA and protein levels." (PMID 38474372, 2024).